ASXL1 (ASXL transcriptional regulator 1)
Diseases named in the same sentence as ASXL1 in open-access papers (continued):
Sharing a sentence is not in itself a finding about the gene and the disease.
mastocytosis (7 papers, 2012 to 2026). A clonal myeloproliferative neoplasm characterized by the proliferation and accumulation of neoplastic mast cells in one or multiple organs or organ systems. "ASXL1 gene is involved in the regulation of histone methylation by cooperation with heterochromatin protein-1 to modulate the activity of LSD1 and ASXL1 mutation was found in three patient with mastocytosis." (PMID 22905207, 2012). "In addition to TET2, ASXL1 appears to also be frequently mutated in patients with mastocytosis (12%-20% cases)." (PMID 26158763, 2015). "In conclusion, TET2, DNMT3A and ASXL1 mutations are also present in mastocytosis and these mutations may affect prognosis, as demonstrated by worse OS in mutated patients." (PMID 22905207, 2012). "The identification of TET2, DNMT3A and ASXL1 mutations in mastocytosis suggest that these defects may alter the epigenetic machinery of the hematopoietic cells in myeloid malignancies, including mastocytosis." (PMID 22905207, 2012). "Moreover, genes whose products influence epigenetic processes including TET2, DNMT3A or ASXL1 may be altered (mutated) in mastocytosis." (PMID 33803981, 2021). "Taken together, these studies suggest that cooperation between KIT and TET2 mutations is likely to contribute to the pathogenesis of mastocytosis; the possibility that ASXL1 also plays a role in this process cannot be ruled out." (PMID 26158763, 2015). "Overall, these clinical findings suggest that the presence of ASXL1 mutations, besides KIT and TET2 may also contribute to the prognosis and survival of mastocytosis patients." (PMID 26158763, 2015). "In the current article, we provide an overview of epigenetic changes that may occur and be relevant to mastocytosis, including mutations in genes involved in epigenetic processes, such as TET2, DNMT3A and ASXL1, and global and gene-specific methylation patterns in neoplastic cells." (PMID 33803981, 2021).
polycythemia vera (7 papers, 2019 to 2025). "Other mutations described in polycythemia vera include ASXL1 and EZH2." (PMID 35456443, 2022). "This contrasts with the single KO mice in which Asxl1 KO mice were largely normal with mild polycythemia vera–like or essential thrombocythemia–like hematopoietic phenotypes noted in some animals, whereas Ezh2 KO resulted in low penetrant MDS/MPN LPDs with extended disease latency." (PMID 40561338, 2025).
coronary heart disease (6 papers, 2020 to 2026). "Mutations in ASXL1 are associated with increased risks of coronary heart disease and ischemic stroke." (PMID 33114351, 2020). "Furthermore, the trial identified specific mutations in DNMT3A, TET2, ASXL1, and JAK2 as independent contributors to heightened coronary heart disease risk." (PMID 41458386, 2025). "In a study that included subjects with coronary heart disease and controls, each major CHIP‐driving mutations, DNMT3A, TET2, ASXL1, and JAK2, was associated with an increased risk of coronary heart disease, but the hazard ratio was the lowest for the DNMT3A mutation." (PMID 36807865, 2023). "Nested case–control analyses of prospective cohorts, that together enrolled 4726 participants with coronary artery disease and 3529 controls, revealed that carriers of CHIP (DNMT3A, TET2 and ASXL1 mutations) have a risk of coronary artery disease that is substantially greater than controls." (PMID 33861346, 2021).
essential thrombocythemia (6 papers, 2017 to 2025). A chronic myeloproliferative neoplasm that involves primarily the megakaryocytic lineage. "The co-occurrence of CALR and ASXL1 mutations has been reported to be enriched in patients affected by essential thrombocythemia (ET)." (PMID 37749078, 2023).
heart failure (6 papers, 2022 to 2025). Inability of the heart to pump blood at an adequate rate to meet tissue metabolic requirements. "Our results suggest that germline variants in ASXL1, including unreported ones, also predispose to heart failure." (PMID 39322779, 2024). "In subset analyses, ASXL1 remained strongly associated with incidence of heart failure (37.7% vs 5.2%; P < .001), CAD (13.5% vs 3.2%; P = .01), and stroke (11.7% vs 1.2%; P < .001) (eTable 5 in Supplement 1)." (PMID 37938837, 2024). "An example of particular interest is a previously unreported association between additional sex combs like 1 (ASXL1) and heart failure." (PMID 39322779, 2024). "In particular, somatic mutations of ASXL1 have been shown to be associated with heart failure and reduced left ventricular ejection fraction both in humans and mice." (PMID 39322779, 2024). "The underlying mechanisms by which CHIP and its mutations in ASXL1, DNMT3A, TET2, or JAK2 are related to heart failure development and progression are not well understood." (PMID 35657494, 2022).
lymphoma (6 papers, 2017 to 2025). A malignant (clonal) proliferation of B- lymphocytes or T- lymphocytes which involves the lymph nodes, bone marrow and/or extranodal sites. "According to the multiple-hit theory of genetic alterations in lymphoma and multiple myeloma, we further analyzed the additional risk factors for the survival of ASXL1+ AML patients." (PMID 34627254, 2021). "The genes EHHADH, INTU, PEX7, and ASXL1 were found to have a significantly higher burden of deleterious variants in cases than controls; variants in these genes may contribute to risk of lymphoid cancers in specific individuals." (PMID 37379307, 2023). "Four genes, INTU (p-value 0.005), ASXL1 (p-value 0.009), EHHADH (p-value 0.03) and PEX7 (p-value 0.02), were associated with lymphoid cancer after multiple testing correction for 7 genes when GnomAD exomes were used as controls." (PMID 37379307, 2023). "Since affected family members of both cases did not have the same variant in ASXL1 or EHHADH, it is plausible that other factors contribute to familial lymphoid cancer in these families." (PMID 37379307, 2023).
melanoma (6 papers, 2017 to 2024). A malignant, usually aggressive tumor composed of atypical, neoplastic melanocytes. "We noted recurring missense mutations relevant to the ‘NEF’ loop in cBioPortal: Glu330 in ASXL2 is mutated in breast, bladder, and urothelial tumours; His315 in ASXL1 in colon, colorectal, lung cancer, and melanoma patient samples." (PMID 30258054, 2018).
neutropenia (6 papers, 2014 to 2025). A decrease in the number of neutrophils found in the blood. "In univariate analysis, the presence of C-findings, the AHNMD subtypes (SM-MDS/CMML/AML versus SM-MPN/hypereosinophilia) (p = 0.044), Neutropenia (p = 0.015), high monocyte level (p = 0.015) and the presence of ASXL1 mutation had detrimental effects on OS (p = 0.007)." (PMID 24465546, 2014). "Finally, 68% of the tested cases displayed at least one somatic mutation, most commonly SF3B1, TET2, ASXL1, and SRSF2, associated with older age, presence of neutropenia, and lower response to ESAs." (PMID 35392224, 2022). "At 6 months, mutants with Asxl1 truncations in our study mainly displayed MDS with neutrophilic dysplasia, which presented as refractory neutropenia." (PMID 33483612, 2021).
systemic mastocytosis (6 papers, 2012 to 2025). Systemic mastocytosis (SM) comprises a heterogeneous group of rare acquired and chronic hematological malignancies that are related to an abnormal proliferation of mast cells in tissue, including bone marrow, with or without skin involvement. "Other somatic gene alterations implicated in some cases of advanced systemic mastocytosis include mutations in TET2, SRSF2, ASXL1, RUNX1, CBL, JAK2, NRAS, and KRAS." (PMID 41440762, 2025). "Interestingly, NGS analysis did not detect any mutations in all the other KIT exons analyzed nor in other genes previously reported in patients with advanced systemic mastocytosis (TET2, SRSF2, ASXL1, RUNX1, CBL, JAK2, NRAS, and KRAS)." (PMID 41440762, 2025).
acute leukemia (5 papers, 2020 to 2025). A clonal (malignant) hematopoietic disorder with an acute onset, affecting the bone marrow and the peripheral blood. "A concomitant ASXL1 mutation at 39% VAF increased to 48% VAF upon transformation to mixed phenotype acute leukemia (MPAL), which has both myeloid and lymphoid features." (PMID 35200567, 2022). "Six studies reported the number of patients transformed to acute leukemia in ASXL1 mutations and wild-type PMF patients." (PMID 33386934, 2021). "Many studies have suggested that ASXL1 mutations are predictive of poor OS and a high risk of acute leukemia transformation for PMF patients, which are adverse factors for the prognosis of PMF patients." (PMID 33386934, 2021). "Co-mutations varied by subtype; MDS/MPN, NOS, and CMML cases frequently harbored mutations in epigenetic regulators (ASXL1, TET2) and splicing factors (SF3B1, SRSF2, ZRSR2), while acute leukemia cases showed alterations in JAK3, STAT3, and NRAS." (PMID 40806796, 2025).
leukocytosis (5 papers, 2015 to 2024). "At 9 months post-BMT, mice harboring combined RUNX1 and ASXL1 mutations developed disease characterized by marked splenomegaly, hepatomegaly, and leukocytosis with a shorter latency." (PMID 31640815, 2019). "Finally, and although there are only two ASXL1+ patients in the AML‐NOS control group, we observe some common characteristics with AML‐MRC patients with ASXL1 mutation, highlighting the presence of leukocytosis in both and myelomonocytic morphological subtype." (PMID 32216059, 2020).
lung carcinoma (5 papers, 2013 to 2025). "The genes upregulated by Asxl1 KO are associated with poor survival, and the genes downregulated by Asxl1 KO are associated with good survival in lung cancer patients." (PMID 30389914, 2018). "This phenomenon could be explained by smoking, which is a well-known high-risk factor of lung cancer and is highly related to mutations in ASXL1." (PMID 40679991, 2025). "Survival analysis using two lung cancer databases revealed better survival when ASXL1 expression was higher." (PMID 30389914, 2018). "Our findings provide considerable insight into the tumor-suppressive role of ASXL1 in lung cancer and will facilitate the development of novel diagnosis and treatment strategies of pulmonary disorders including respiratory distress syndrome." (PMID 30389914, 2018). "Unlike our study, they found that mutations in ASXL1 exhibited a higher risk of lung cancer than DNMT3A and TET2." (PMID 40679991, 2025). "Hematologic progression occurred simultaneously with an ASXL1-R693X-negative lung-cancer." (PMID 24011025, 2013). "Lung cancer patients with high levels of ASXL1 expression and lower levels of NMYC expression showed better survival, suggesting a close link between ASXl1 and NMYC." (PMID 30389914, 2018).
microcephaly (5 papers, 2018 to 2025). A congenital or acquired developmental disorder in which the circumference of the head is smaller than normal for the person's age and sex. "In this study, we demonstrate that Asxl1 deletion in mice induces microcephaly, primarily caused by a reduction in the size and number of cortical neurons." (PMID 40276524, 2025). "However, the head sizes of our proband were normal, which is contrary to the microcephaly reported in every other case with ASXL1 disease-causing variants." (PMID 35119035, 2022). "Our findings highlight a critical role for Asxl1 in maintaining NSC survival and neurogenesis through its interaction with EZH2, providing insights into the mechanisms underlying microcephaly and developmental disorders associated with ASXL1 mutations." (PMID 40276524, 2025). "Our findings demonstrate that loss of Asxl1 results in phenotypes characteristic of BOS, including microcephaly and cortical thinning." (PMID 40276524, 2025). "In addition to cyanosis, Asxl1−/− neonates showed a small body and lung size, anophthalmia, microcephaly, and cleft palates compared to wild-type (WT) neonates after birth." (PMID 30389914, 2018).
multiple myeloma (5 papers, 2016 to 2025). "These novel driver mutations hit histone proteins (HIST1H1D; HIST1HIC) involved in resistance to lenalidomide in multiple myeloma (IKZF3), nuclear RNA export factor 1 (NXF1) and proteins also mutated in acute myeloid leukemia and multiple myeloma (ASXL1; TRAF3)." (PMID 27580852, 2016).
Anophthalmia (4 papers, 2018 to 2025). Absence of the globe or eyeball. "In this study, we demonstrated that anophthalmia in Asxl1 knockout (KO) mice is caused by impaired optic cup (OC) formation at E10.5." (PMID 40766969, 2025). "Depending on the model, Asxl1 loss causes embryonic lethality and developmental abnormalities, including dwarfism, anophthalmia, microcephaly, kidney podocyte defects, and craniofacial defects." (PMID 30389914, 2018). "Taken together, this study provides valuable insights into the molecular mechanisms of Asxl1 in eye development and its potential involvement in the etiology of developmental eye disorders such as anophthalmia and microphthalmia." (PMID 40766969, 2025). "Previous studies using Asxl1 KO mice have revealed developmental defects, including microcephaly, cleft palate, alveolar maturation defects, glomerular podocyte abnormalities, and anophthalmia." (PMID 40766969, 2025). "Similarly, Wang and colleagues (2014) reported that homozygous constitutive inactivation of Asxl1 in mice led to dwarfism and anophthalmia." (PMID 31064769, 2019). "We did not observe craniofacial abnormalities or anophthalmia, both of which have been reported in the murine models with Asxl1 deletion." (PMID 31064769, 2019).
aplastic anemia (4 papers, 2019 to 2024). Anemia resulting from bone marrow failure (aplastic or hypoplastic bone marrow). "BCORL1 and ASXL1 mutations are mainly seen in hematologic malignancies and aplastic anemia." (PMID 38142265, 2024). "We observed only one mutation of the ASXL1 gene in a patient with aplastic anemia." (PMID 33500526, 2021).
developmental delays (4 papers, 2020 to 2024). "Here, we present developmental phenotyping data on individuals with Bohring-Optiz Syndrome (BOS – ASXL1) and Bainbridge-Ropers Syndrome (BRS – ASXL3) related disorders, two CMDs highly penetrant for motor and developmental delays." (PMID 38027485, 2023).
Hypertension (4 papers, 2022 to 2026). The presence of chronic increased pressure in the systemic arterial system. "ASXL1-CHIP also showed directional risk elevations for intracerebral hemorrhage and hypertension." (PMID 42131836, 2026). "However, it is unclear why ASXL1 is associated with essential hypertension and CHIP DNMT3A mutations have been associated with hypertension in human patients and mice." (PMID 37059828, 2023). "The association with SSTR2, ASXL1, and ATOH1 may suggest potential novel mechanism in the pathogenesis of hypertension that needs to be to further elucidated." (PMID 37059828, 2023). "Thus, the SSTR2, ATOH1 and ASXL1 genes are all novel hypertension candidate genes." (PMID 37059828, 2023).
myopia (4 papers, 2018 to 2025). "It was found that high myopic associated proteins (ASXL1 FGFR3 ERBB3 SOX4) can affect ARID1B protein by affecting ARIDIA protein, and COL2A1 protein can also affect ARIDIA protein by affecting FGFR3 protein, resulting in the clinical phenotype of patients with high myopia." (PMID 38790056, 2024). "Analysis of protein interactions in the STRING online database revealed that the ARID1A protein interacts with the high myopia gene-related proteins FGFR3, ASXL1, ERBB3, and SOX4, whereas the ARID1A protein antagonizes the ARID1B protein." (PMID 38790056, 2024).
Obesity (4 papers, 2023 to 2025). Accumulation of substantial excess body fat. "Further, they performed experiments using mouse models of obesity with Ob/Ob mice and showed an accelerated expansion of hematopoietic stem and progenitor cells (HSPCs) harboring Tet2, Dnmt3a, Asxl1, or Jak2 mutation." (PMID 40773119, 2025). "Notably, it is of particular interest that pro-atherogenic conditions—possibly including obesity—appear to overcome the previously reported competitive disadvantage associated with ASXL1 mutations." (PMID 40773119, 2025). "To investigate the relationship between CHIP and obesity, we analyzed several mouse models harboring common CHIP mutations: Tet2, Dnmt3a, Asxl1, or Jak2 on the background of LepOb/Ob (Ob/Ob) mice to mimic the human pre-LHSCs/PCs condition occurring in individuals with obesity." (PMID 37071471, 2023). "Considering these findings, ASXL1-CH is likely to expand with acceleration in atherogenic conditions, including dyslipidemia and obesity." (PMID 40773119, 2025). "Mouse models of obesity and CHIP driven by heterozygosity of Tet2, Dnmt3a, Asxl1, and Jak2 resulted in exacerbated expansion of mutant HSC/Ps due in part to excessive inflammation." (PMID 37071471, 2023).
prostate carcinoma (4 papers, 2019 to 2024). A carcinoma that arises from epithelial cells of the prostate gland. "ASXL1 is a scaffold protein and variants have been found in different types of cancers, such as in breast, hematological cancers and prostate cancer, conferring to this protein the role of a tumor suppressor." (PMID 33572923, 2021). "Thus, we searched for germinal variants in ASXL1, CHD1, IDH1, SETD2 and TET2 epigenetic genes in Polish prostate cancer patients and controls and analyzed the impact of them on disease clinical course, including overall survival time." (PMID 39529133, 2024).
Wilms tumor (4 papers, 2019 to 2024). An embryonal neoplasm characterized by the presence of epithelial, mesenchymal, and blastema components. "In subject 2, a Wilms tumor; there were less oncogenic events, and ASXL1 S577* hotspot mutation was shared across all whereas MYCN P44L was present in later biopsies." (PMID 38347552, 2024). "A further five constitutionally mutated genes—PIK3CA, FBXW7, ASXL1, BRCA2, and CDC73—were somatically mutated in other cancer types but have not been proven to be somatic drivers in Wilms tumour." (PMID 30885698, 2019).
Bainbridge-Ropers syndromes (3 papers, 2020 to 2023). "The de novo truncating variants in ASXL1-3 proteins serve as the genetic basis for severe neurodevelopmental diseases such as Bohring-Opitz, Shashi-Pena, and Bainbridge-Ropers syndromes, respectively." (PMID 32132929, 2020). "Indeed, germ-line de novo truncating variants in human ASXL1, ASXL2, and ASXL3 cause the congenital and developmental disorders Bohring-Opitz, Shashi-Pena, and Bainbridge-Ropers syndromes, respectively, and somatic mutations of ASXL1, ASXL2, and ASXL3 occur in solid and hematologic malignancies." (PMID 36068610, 2022).
diabetes (3 papers, 2020 to 2025). "Conversely, AF patients with CHIP (especially with TET2 and ASXL1 alterations) face a 23% higher diabetes risk." (PMID 40804878, 2025). "From a biological perspective, mutations involved with leukemogenesis (DNMT3A, TET2, and ASXL1) are also enriched in patients with diabetes and atherosclerotic disease but without cancer." (PMID 33709085, 2020).
Intellectual disability (3 papers, 2020 to 2023). "More importantly, mutations in ASXL1 have been associated with Boring Opitz Syndrome (605039), which has been characterized by profound intellectual disability." (PMID 32522152, 2020).